TCF12 (transcription factor 12)
Description:
Transcriptional regulator. Involved in the initiation of neuronal differentiation. Activates transcription by binding to the E box (5'-CANNTG-3') (By similarity). May be involved in the functional network that regulates the development of the GnRH axis.
Synonyms: TCF-12; bHLHb20; HEB; HTF4; HsT17266; p64; CRS3; HH26
Tractability: PROTAC: UniProt records ubiquitination sites on it; ubiquitination databases record sites on it; its protein half-life has been measured.
Target class: Transcription factor
Gene: Protein-coding gene on chromosome 15 (56,918,099 to 57,299,707, forward strand). Ensembl gene ENSG00000140262.
Subcellular location: Nucleus
Subcellular location (Human Protein Atlas): Nuclear speckles; Nucleoplasm
Pathways (Reactome):
Signal Transduction: NGF-stimulated transcription; TGFBR3 expression
Cell-Cell communication: Negative Regulation of CDH1 Gene Transcription
Chromatin organization: CHD1 and CHD2 subfamily
Developmental Biology: Myogenesis
Gene expression (Transcription): RUNX1 regulates transcription of genes involved in differentiation of HSCs
Gene Ontology:
Molecular function: bHLH transcription factor binding; DNA-binding transcription activator activity, RNA polymerase II-specific; DNA-binding transcription factor activity; DNA-binding transcription factor binding; protein binding; RNA polymerase II cis-regulatory region sequence-specific DNA binding; sequence-specific double-stranded DNA binding; SMAD binding; transcription cis-regulatory region binding; cis-regulatory region sequence-specific DNA binding; DNA-binding transcription factor activity, RNA polymerase II-specific; cAMP response element binding; HMG box domain binding; protein dimerization activity
Biological process: positive regulation of transcription by RNA polymerase II; response to gonadotropin-releasing hormone; immune response; muscle organ development; nervous system development; regulation of transcription by RNA polymerase II; positive regulation of DNA-templated transcription
Cellular component: chromatin; cytoplasm; nuclear speck; nucleoplasm; nucleus; RNA polymerase II transcription regulator complex; transcription regulator complex
Genetic constraint (gnomAD): Loss-of-function variants: 29 observed, 64.92 expected, observed/expected ratio (o/e) 0.45, 90% interval 0.33 to 0.61. The upper end of that interval is the gene's LOEUF score, 0.61, which puts it in group 2 of 6, group 1 being the genes least tolerant of losing a copy. Missense variants: 785 observed, 809.19 expected, observed/expected ratio (o/e) 0.97, 90% interval 0.91 to 1.03. Synonymous variants: 302 observed, 291.4 expected, observed/expected ratio (o/e) 1.04, 90% interval 0.94 to 1.14.
Gene-disease validity (ClinGen):
ClinGen rates the evidence that TCF12 causes each of these diseases.
TCF12-related craniosynostosis (autosomal dominant): Definitive.
Homologues: Orthologues: macaque TCF12 (99% identical), chimpanzee TCF12 (99% identical), pig TCF12 (96% identical), rat Tcf12 (96% identical), mouse Tcf12 (96% identical), dog TCF12 (95% identical), rabbit TCF12 (94% identical), guinea pig TCF12 (89% identical), tropical clawed frog tcf12 (83% identical), zebrafish tcf12 (55% identical), Drosophila melanogaster da (28% identical), Caenorhabditis elegans hlh-2 (15% identical). Paralogues in human: TCF4 (59% identical), TCF3 (50% identical).
Diseases named in the same sentence as TCF12 in open-access papers:
TCF12 is named in the same sentence as 94 diseases in open-access papers, as found by Europe PMC text mining. Sharing a sentence is not in itself a finding about the gene and the disease. The quoted sentences say what the papers report.
craniosynostosis (22 papers, 2013 to 2025). Craniosynostosis is defined as the premature fusion of one or more cranial sutures leading to secondary distortion of skull shape resulting in skull deformities with a variable presentation. "The craniosynostosis-causing pathogenic variants described in TCF12 are mainly located either in or near the bHLH domain and result in a frameshift and/or premature stop codon." (PMID 40287710, 2025). "Phenotypically all three patients with TCF12 variants exhibit coronal synostosis which is typical in TCF12 related craniosynostosis." (PMID 40287710, 2025). "For instance, the TCF12 gene encoding the bHLH (basic helix-loop-helix) protein TCF12 (transcription factor 12) is linked to Craniosynostosis 3 (OMIM: 615314) which exhibits a Saethre-Chotzen (OMIM:101400) like phenotype." (PMID 40287710, 2025). "LOF variants in the TCF12 gene are associated with Craniosynostosis 3 (OMIM: 615314), which shows a Saethre-Chotzen (OMIM:101400) like phenotype." (PMID 40287710, 2025). "TCF12 is a known and well-studied gene related to craniosynostosis, and pathogenic splice site variants are already described as potentially disease causing." (PMID 40287710, 2025). "Patients with heterozygous TCF12 variants frequently exhibit skeletal malformations, facial dysmorphisms, and intellectual problems, in addition to craniosynostosis." (PMID 40642286, 2025). "A more recently identified gene linked to craniosynostosis is TCF12 encoding the bHLH (basic helix-loop-helix) protein TCF12 (transcription factor 12; also called HEB) which belongs to class I proteins, also called E proteins." (PMID 40287710, 2025). "Comparison with previous studies on TCF12 variants in patients with craniosynostosis revealed an accumulation of missense and frameshift variants in the 3’ region of the protein affecting the bHLH domain." (PMID 40287710, 2025). "Intragenic as well as complete TCF12 deletions have also been reported as a cause of craniosynostosis." (PMID 40287710, 2025). "Haploinsufficiency of TCF12 was first known to cause syndromic and non-syndromic craniosynostosis predominantly affecting coronal suture [MIM #615314]." (PMID 39036055, 2024). "TCF12, a recently identified molecular defect, causes craniosynostosis and is suggested to be used as a biomarker for prognosis in various cancer types." (PMID 39036055, 2024). "TCF12 (chr 15q21.3) is a member of the basic helix-loop-helix (bHLH) transcription factors subfamily and TCF12 haploinsufficiency causes premature cranial suture fusion, leading to a rare developmental disorder known as craniosynostosis." (PMID 34502334, 2021). "A recent report highlighted the presence of TCF12 variants in 13 individuals from 12 KS pedigrees, with few cases also presenting with craniosynostosis, implicating a possible genotype–phenotype correlation." (PMID 34502334, 2021). "In humans, mutations in TCF12 lead to craniosynostosis, a congenital birth disorder characterized by the premature fusion of one or several of the cranial sutures." (PMID 31188878, 2019). "Saethre-Chotzen syndrome is caused by mutations in or re-arrangements in TWIST1 and TCF12-related craniosynostosis is caused by mutations or re-arrangements in TCF12." (PMID 30392078, 2019). "Over the last years, a number of different mutations in TCF12 have been identified to cause craniosynostosis in humans." (PMID 31188878, 2019). "Here, we present the identification of four large rearrangements in TCF12 causing TCF12‐related craniosynostosis." (PMID 27158814, 2016). "Overall, three out of 25 Dutch cases of TCF12‐related craniosynostosis were caused by large, intragenic TCF12 rearrangements." (PMID 27158814, 2016). "Our study demonstrates that TCF12‐related craniosynostosis can also be caused by large intragenic rearrangements and that there is no indication of a genotype–phenotype correlation." (PMID 27158814, 2016).
craniosynostosis (continued). "We also recently evaluated a patient (unpublished data) with a right coronal craniosynostosis, left peripheral facial palsy and a TCF12 c.825+1G>C mutation." (PMID 25871887, 2015). "Of recent interest, TCF12 has been implicated in human nonsyndromic craniosynostosis, and we intend to investigate its role in this colony as well." (PMID 23738319, 2013). "Thus far, pathogenic TCF12 variants have been identified mostly in patients with craniosynostosis or other developmental defects." (PMID 40642286, 2025). "Further description of new cases with TCF12 variations could enhance our understanding of craniosynostosis and its potential link to Kallmann syndrome associated with this gene." (PMID 39036055, 2024). "On the other hand, WES analysis revealed a CNV involving exon 1 and exon 6–8 in TCF12 associated with HH and/or craniosynostosis, and a heterozygous missense variant, c.214C>A (p.Leu72Met) rs696217, in GHRL gene (NM_016362) associated with susceptibility to obesity (not shown)." (PMID 39036055, 2024). "Targeted PCR and Sanger sequencing of FGFR1, FGFR2, FGFR3, TWIST1, and TCF12 genes resulted in the highest diagnostic rate in our cohort of craniosynostosis patients strongly recommend analysing those genes first (isolated CS and syndromic CS without intellectual disability)." (PMID 35591945, 2022). "Several TCF12 mutations have been identified in TCF12 from individuals with craniosynostosis." (PMID 33937142, 2021). "Saethre-Chotzen syndrome or TCF12-related craniosynostosis present a genetic close relationship and most of the phenotypic features related to TCF12-related craniosynostosis mutations or re-arrangements resemble those of Saethre-Chotzen syndrome with a large clinical spectrum." (PMID 30392078, 2019). "Heterozygous mutations in TCF12 were recently identified as an important cause of craniosynostosis." (PMID 25871887, 2015). "Taken together, the in-frame deletion of 69 amino acids in the AD2 domain, due to aberrant splicing, influences the activity of TCF12 which explains the bilateral craniosynostosis phenotype in P1." (PMID 40287710, 2025). "In the past, Muenke syndrome, Saethre-Chotzen syndrome, and TCF12-related craniosynostosis were often undiagnosed or misdiagnosed because of the mild and sometimes overlapping clinical features." (PMID 34904178, 2022). "Smaller maxillary dental arch dimensions also have been found in Muenke syndrome, Saethre-Chotzen syndrome, and TCF12-related craniosynostosis." (PMID 34904178, 2022). "In this study, we showed that the midface is hypoplastic in Muenke syndrome, Saethre-Chotzen syndrome, and TCF12-related craniosynostosis compared to the Dutch control group." (PMID 34904178, 2022). "This retrospective case–control study indicates that children with Muenke syndrome, Saethre-Chotzen syndrome, and TCF12-related craniosynostosis have distinctive skeletal and dental characteristics." (PMID 34904178, 2022). "Lastly, patients with TCF12-related craniosynostosis had decreased PC1, PC2, PC3, and PC4 compared to the controls, adjusted for age and sex." (PMID 34904178, 2022). "Patients with Muenke syndrome, Saethre-Chotzen syndrome, and TCF12-related craniosynostosis have a more vertical craniofacial buildup compared to the control group." (PMID 34904178, 2022). "The midface is hypoplastic in Muenke syndrome, Saethre-Chotzen syndrome, and TCF12-related craniosynostosis compared to those of the Dutch controls." (PMID 34904178, 2022). "In our visual presentation of TCF12-related craniosynostosis, the mandible (SNB) has an increased value, and the jaw relationship (ANB) has a decreased value." (PMID 34904178, 2022). "The overall results of our measurements are presented in the visual presentations of Muenke syndrome, Saethre-Chotzen syndrome, and TCF12-related craniosynostosis." (PMID 34904178, 2022).
craniosynostosis (continued). "The jaw complex and dental relationship (PC3), which is characterized by NL/ML and interincisal angle, were not different in Muenke syndrome, Saethre-Chotzen syndrome, and TCF12-related craniosynostosis compared to the Dutch controls." (PMID 34904178, 2022). "Differences were found in age (p = 0.012) but not in sex (p = 0.568) between Muenke syndrome, Saethre-Chotzen syndrome, TCF12-related craniosynostosis, and the controls." (PMID 34904178, 2022). "The more hyperdivergent jaw complex is also seen in Muenke syndrome and TCF12-related craniosynostosis." (PMID 34904178, 2022). "Lastly, patients with TCF12-related craniosynostosis had an increased SNB (p = 0.011), decreased ANB (p = 0.015), decreased NSL/NL (p = 0.026), increased SN/ML (p < 0.001), increased NL/ML (p = 0.001), and decreased NSL/BOP (p = 0.001) compared to controls." (PMID 34904178, 2022). "The aim of our study is to compare the skeletal, sagittal, and vertical cephalometric dimensions of patients with Muenke syndrome, Saethre-Chotzen syndrome, and TCF12-related craniosynostosis to the individuals of a control group of healthy Dutch children." (PMID 34904178, 2022). "Previously reported shared clinical features of Saethre-Chotzen syndrome and TCF12-related craniosynostosis are now supported by our cephalometric findings." (PMID 34904178, 2022). "The maxillary growth in patients with Muenke syndrome, Saethre-Chotzen syndrome, or TCF12-related craniosynostosis is impaired, leading to a deviant dental development." (PMID 34904178, 2022). "The study population consisted of 43 patients with Muenke syndrome, 22 with Saethre-Chotzen syndrome, 9 with TCF12-related craniosynostosis, and 208 controls." (PMID 34904178, 2022). "The skeletal pattern and jaw complex in TCF12-related craniosynostosis are more hyperdivergent compared to the Dutch controls." (PMID 34904178, 2022). "Genetic confirmation for Muenke syndrome, Saethre-Chotzen syndrome, and TCF12-related craniosynostosis has been possible for several years." (PMID 34904178, 2022). "SNB has an increased value in Muenke syndrome and TCF12-related craniosynostosis, which can be explained by significantly more counterclockwise rotation of the mandible that is the result of a more anterior rotation of the palatal plane angle." (PMID 34904178, 2022). "Based on the craniofacial knowledge in the Apert and Crouzon syndrome, we expect that similar craniofacial characteristics should be present in a lesser extent in Muenke syndrome and Saethre-Chotzen syndrome or TCF12-related craniosynostosis." (PMID 30392078, 2019). "In this study, we showed that the maxilla and mandible in Muenke and Saethre-Chotzen syndromes or TCF12-related craniosynostosis are smaller in the transverse dimension compared to those of the control group." (PMID 30392078, 2019). "The mandibular IMW was not statistically significantly different in the Saethre-Chotzen syndrome or the TCF12-related craniosynostosis than those of the control group (β = − 0.07, 95% CI − 1.45, 1.31)." (PMID 30392078, 2019). "Patients with Muenke syndrome and Saethre-Chotzen syndrome or TCF12-related craniosynostosis can more easily be overlooked compared with children with Apert and Crouzon syndrome." (PMID 30392078, 2019). "The ratio for the ICW was not statistically significantly different in the Saethre-Chotzen syndrome or the TCF12-related craniosynostosis patients (ICW, p = 0.191)." (PMID 30392078, 2019). "The ratio for the IMW was statistically significantly smaller in the Saethre-Chotzen syndrome or the TCF12-related craniosynostosis patients than those of the control group (p = 0.006)." (PMID 30392078, 2019). "The study population consisted of 34 patients with Muenke syndrome, 8 patients with Saethre-Chotzen syndrome, 6 patients with TCF12-related craniosynostosis syndrome, and 329 healthy children." (PMID 30392078, 2019).
craniosynostosis (continued). "Understanding the regulation of the gene expression of genes like tcf12, that are involved in developmental defects like craniosynostosis, is therefore important for understanding the disease mechanism and to find a treatment for the patients in the long term." (PMID 31188878, 2019). "The mean age of Muenke syndrome and Saethre-Chotzen syndrome or TCF12-related craniosynostosis was, respectively, 8.95 years (SD 2.63) and 8.97 years (SD 2.04)." (PMID 30392078, 2019). "In this study, we showed that the dental arches of the maxilla and the mandible of patients with Muenke syndrome and Saethre-Chotzen syndrome or TCF12-related craniosynostosis are smaller compared to those of a control group." (PMID 30392078, 2019). "Of the 14 patients with Saethre-Chotzen syndrome or TCF12-related craniosynostosis, 5 children were boys and 9 children were girls." (PMID 30392078, 2019). "As seen in Apert and Crouzon patients, patients with Muenke and Saethre-Chotzen syndromes or TCF12-related craniosynostosis are prone to have posterior crossbites." (PMID 30392078, 2019). "The maxillary IMW in the Saethre-Chotzen syndrome or the TCF12-related craniosynostosis was statistically significantly smaller than those of the control group (β = − 3.40, 95% CI − 4.78, − 2.02)." (PMID 30392078, 2019). "The ratios for the AD and AL were not statistically significantly different in the Saethre-Chotzen syndrome or the TCF12-related craniosynostosis patients and those of the control group (AD, p = 0.300 and AL, p = 0.672, respectively)." (PMID 30392078, 2019). "In summary, we have identified the first intragenic duplication and deletions within TCF12 in patients with craniosynostosis." (PMID 27158814, 2016). "However, some intragenic and multigenic CNVs of TCF12 were reported in patients with craniosynostosis and/or neurodevelopmental problems." (PMID 39036055, 2024). "Interestingly, haploinsufficiency of TCF12 was detected both in patients with craniosynostosis and HH." (PMID 39036055, 2024). "Regarding the incomplete penetrance, variable expressivity, and pleiotropy of TCF12-related disorders, patients could display variable phenotypic features such as intellectual disability, developmental delay, and craniosynostosis." (PMID 39036055, 2024). "TCF12 haploinsufficiency is a cause of syndromic and non-syndromic craniosynostosis (craniosynostosis-3, MIM #615314)." (PMID 39036055, 2024). "The vertical growth pattern, jaw complex, and proclination of the upper incisors (PC2), which is characterized by NSL/NL, NL/ML, and Ils/NL, were decreased in the Muenke syndrome and TCF12-related craniosynostosis compared to patients of the Dutch control group." (PMID 34904178, 2022). "After Bonferroni correction of the outcomes with ANOVA analysis, we found that SNB, ANB, NSL/NL, SN/ML, NL/ML, and NSL/BOP differed statistically significant between patients with Muenke syndrome, Saethre-Chotzen syndrome, TCF12-related craniosynostosis, and the controls." (PMID 34904178, 2022). "Because the mutation that causes TCF12-related craniosynostosis is recently discovered, no distinctive main features of this syndrome has been reported to date." (PMID 34904178, 2022). "Cephalometric values comprising the midface were decreased in Muenke syndrome (ANB: β = –1.87, p = 0.001; and PC1: p < 0,001), Saethre-Chotzen syndrome (ANB: β = –1.76, p = 0.001; and PC1: p < 0.001), and TCF12-related craniosynostosis (ANB: β = –1.70, p = 0.015; and PC1: p < 0.033)." (PMID 34904178, 2022). "All dental arch dimensions in Muenke (ICW, IMW, AL, p < 0.001, ADmax, p = 0.008; ADman, p = 0.002), Saethre-Chotzen syndrome, or TCF12-related craniosynostosis patients (ICWmax, p = 0.005; ICWman, IMWmax, AL, p < 0.001) were statistically significantly smaller than those of the control group." (PMID 30392078, 2019).